IL6 (interleukin 6)
Diseases named in the same sentence as IL6 in open-access papers (continued):
Sharing a sentence is not in itself a finding about the gene and the disease.
COVID-19 (continued). "Using data from a unique makeshift hospital for COVID-19 patients, this results from this retrospective study showed that higher serum levels of IL-6 was an independent and reliable risk factor for COVID-19 patients and led to higher disease severity and mortality." (PMID 32765283, 2020). "Thus, we aim to observe the association of coagulopathy (D-dimer) with cytokine (i.e., IL-6) and CT imaging in COVID-19-infected patients." (PMID 33195321, 2020). "Such anti-arrhythmic potential may further support the application of tocilizumab in COVID-19 patients to counteract the risk of adverse QT prolongation and related life-threatening arrhythmias associated with elevated IL-6 and the anti-viral agents." (PMID 32426374, 2020). "Interleukin-6 (IL-6), a proinflammatory cytokine, has been reported to be associated with disease severity and mortality in patients with coronavirus disease 2019 (COVID-19)." (PMID 32765283, 2020). "Moreover, studies have reported that pro-inflammatory factors such as CRP, interleukin 6, neutrophils, etc. were associated with the severity and prognosis of patients with COVID-19." (PMID 33192519, 2020). "The pathogenic aspects regarding the IL-6 in COVID-19 will be addressed below." (PMID 32962761, 2020). "Given the deleterious effects of hypercytokinemia in severe COVID-19 and association of IL-6 with disease severity, genetic variants that cause altered cytokine signaling might be among the host genetic factors for severe COVID-19 susceptibility." (PMID 33414783, 2020). "There are 306 ongoing registered trials for the treatment of COVID-19 as of 4 April 2020, including trials of IL-6- and IL-6-receptor (IL-6R)-blocking antibodies, as severe COVID-19 causes strong expression of chemokines and inflammatory cytokines, especially IL-6 and IL1RA." (PMID 32850443, 2020). "Macrophage activation syndrome (MAS) was reported in several COVID-19 patients with severe respiratory failure, and the production of associated pro-inflammatory cytokines (IL-6 and TNFα) might contribute to hyper-inflammatory conditions." (PMID 32760407, 2020). "Moreover, in severe/critical COVID-19 patients the increase and reduction of the IL-6:AAT ratio has been associated with a poor outcome and clinical improvement, respectively." (PMID 33195215, 2020). "Several markers were associated with COVID-19 severity, the most accepted is IL-6." (PMID 32873316, 2020). "IL-6 is involved in physiological hematopoiesis and response to pathogens but excessive production is associated with disorders that resemble severe COVID-19 manifestations, such as the hemophagocytic lymphohistiocytosis, and the cytokine release syndrome induced by CAR-T-cell." (PMID 33442386, 2020). "SARS-CoV-2 infection of human monocytes in vitro recapitulates most of the pattern of inflammatory mediator production associated with COVID-19 severity, including the enhancement of the IL-6 and TNFα levels, and the consistent cell death, measured by LDH release." (PMID 33326472, 2020). "Indeed, in patients with COVID-19, it has been reported that IL-6 level is significantly elevated and associated with adverse clinical outcomes including severity and mortality of COVID-19 in published papers and pre-print papers." (PMID 33024459, 2020). "Indeed, IL-6 and serum ferritin, traditionally elevated in proinflammatory conditions, have been associated with higher mortality in patients infected with COVID-19." (PMID 33351817, 2020). "While some of these cytokines (IL-6 and IL-8) have been implicated previously in COVID-19 pathogenesis, our comprehensive screening approach has identified a signature that is notable for its focus on largely innate inflammatory mediators associated with monocyte and neutrophil mobilization." (PMID 33187979, 2020).
COVID-19 (continued). "Several groups have analyzed cytokine levels in plasma or sera of COVID-19 patients and demonstrated elevated levels of proinflammatory cytokines such as IL-6 and TNFα and their strong association with disease severity, leading to the concept of a cytokine storm." (PMID 33262067, 2020). "This may be due to increased expression of cytokines, including interleukin (IL)-2, IL-6, IL-7, tumor necrosis factor, granulocyte colony-stimulating factor, interferon-gamma, and free radicals associated with the severity of COVID-19." (PMID 32953353, 2020). "In line with these clinical observations, severe COVID-19 is also associated with increased concentrations of proinflammatory cytokines including IL-6 which can induce tissue factor expression on mononuclear cells that initiates coagulation, platelet activation and thrombin generation." (PMID 33062058, 2020). "Moreover, a similar association between IL-6 levels and CT scores was observed in COVID-19 patients over a period of 20–30 days." (PMID 32765283, 2020). "This study aimed to determine whether patients with elevated CRP, TNFα, and IL-6 levels may be at increased risk for severe infection and liver damage of COVID-19." (PMID 33244370, 2020). "Indeed, studies have demonstrated association of higher Interleukin 6 levels with respiratory failure and requirement for mechanical ventilation in COVID-19 patients." (PMID 32556213, 2020). "It is likely that a higher IL-6 level is an independent risk factor for in-hospital severity and mortality in Chinese COVID-19 patients, and it might be a potential predictor of lung injury in these patients." (PMID 32765283, 2020). "Indeed, elevated serum levels of IL-6 were described to be associated to poorer outcomes, coagulopathy, and increased mortality in patients with COVID-19." (PMID 33442386, 2020). "Levels of SARS-CoV-2 viremia was also associated with markers of inflammation and disease severity, including low lymphocyte counts, and elevated CRP and IL-6 levels." (PMID 33127906, 2020). "Our results showed that a blockade of IL-6 signaling by anti-IL-6/IL-6R/JAK antibodies plus SOC significantly reduced the mortality rate but did not increase the risk of secondary infections compared to SOC alone in patients with COVID-19." (PMID 33384605, 2020). "However, the severe COVID-19 cases showed an increase in IL-6, IL-2R, IL-10, and TNFα secretion associated with a severe decrease in T cells, particularly CD4+ T cells." (PMID 32793246, 2020). "Tocilizumab and lenzilumab are recombinant monoclonal antibodies against IL-6 and granulocyte macrophage colony-stimulating factor, respectively, and have been proposed as a potential treatment for acute, hypoxic respiratory failure associated with COVID-19." (PMID 32546029, 2020). "Thus, all analyses conducted in our study validated that elevated IL-6 levels are an independent risk factor for the severity and mortality of COVID-19." (PMID 32765283, 2020). "Although our study doesn’t have enough numbers of patients to identify biomarkers for severity, our findings of the association between IL-6, IP-10, IL-1ra and RF in COVID-19 provides a foundation for further studies investigating their predictive value for RF." (PMID 33303843, 2020). "SpO2/FiO2 and chest x-ray on admission or changes on inflammatory parameters as IL-6 and ferritin allow us early identification of COVID-19 patients at risk of high-flow-oxygen-support that may benefit from a more intensive disease management." (PMID 33370397, 2020). "Furthermore, elevated serum levels of IL-6 have been reported to be significantly associated with death among severe COVID-19 cases." (PMID 32574265, 2020). "Similarly, one recent study reported that vitamin K deficiency in male COVID-19 patients was associated with greater IL-6 levels in the general circulation." (PMID 33374341, 2020).
COVID-19 (continued). "However, Patients infected with SARS-CoV-2 who have the TNF-α gene variant (rs1800629) are protected from developing COVID-19 moderate and severe outcomes, as well as from presenting low concentrations of some pro-inflammatory cytokines and chemokines (IL-6, CCL2, and CXCL-10)." (PMID 40881695, 2025). "However, cancer patients often have hyperactivated IL-6, which may be another factor affecting COVID-19 severity, as multiple studies have shown that elevated IL-6 concentrations are associated with poor COVID-19 outcomes." (PMID 40489562, 2025). "Therefore, since IL-6 has previously been implicated in severe COVID-19, it may possibly also be involved in the inappropriate hyperactivation of immunity in PIMS/MIS-C." (PMID 39940694, 2025). "However, IL-6, a significant cytokine in COVID-19, is mainly associated with two JAK/STAT pathways." (PMID 41002992, 2025). "IL-6 serum levels have been associated with high risk of poor prognosis in patients with severe COVID-19 so, guiding tocilizumab treatment according to the levels of IL-6 could be a strategy to maximize outcomes, and optimize the proper use of a limited and expensive resource." (PMID 40232661, 2025). "Previous studies have shown that cytokine storms in patients with COVID-19 and other severe infections are significantly associated with high mortality, particularly highlighting the pivotal roles of pro-inflammatory factors such as IL-6 and TNF-α in dysregulated inflammation." (PMID 39774553, 2025). "Moreover, since JAK2 appears to be not involved in type I or type II interferon-signaling, selective Jak-2 specific inhibitors may provide a better outcome for suppressing IL-6-GM-CSF-signaling-in COVID-19-associated cytokine storms." (PMID 40410684, 2025). "The tight correlations we observed between CRP, ferritin, IL-6, and fibrinogen, together with their steep gradients across outcome groups, are consistent with a hyperferritinemic, macrophage-activation-like phenotype that has been repeatedly implicated in critical COVID-19." (PMID 41463074, 2025). "In fact, previous studies also showed severity of COVID-19 is associated with increased levels of inflammatory proteins (interleukin 6), coagulation proteins (VWF and fibrinogen), but a specific link with development of thromboembolic outcome could not be found." (PMID 40224277, 2025). "Moreover, COVID-19 causes a hyper-inflammatory systemic response due to excessive cytokine release, which includes cytokines such as interleukin-6 (IL-6), leading to intrarenal inflammation, increased vascular permeability, and alterations in kidney microcirculation." (PMID 40005354, 2025). "Our hypothesis-driven approach revealed that higher COVID-19 disease severity was associated with an increased number of interactions between IL6 and other multi-omics layers, therefore suggesting that our approach may discriminate between COVID-19 and other respiratory disorders." (PMID 39040605, 2024). "The study authors found that angiotensin receptor blocker use was associated with a significantly improved COVID-19 outcome, in part due to lower circulating levels of mortality-predicting markers, including leukocytes, neutrophils, C-reactive protein, procalcitonin, and IL-6." (PMID 39518552, 2024). "In contrast, IL-8 and to some extent IL-6, which have been shown to be associated with disease severity of COVID-19 and increased in other SARS-CoV-2 infection models, showed a reduction as a response to SARS-CoV-2 infection, which may be due to the absence of immune cells in our model." (PMID 39697363, 2024). "Cytokines such as IL-2, IL-6, TNF-α, IFN-γ, and IL-10 could serve as predictors for early prediction of the severity of COVID-19; hence, this study aimed to evaluate the association of cytokine levels IL-2, IL-6, TNF-α, IFN-γ, and IL-10 with the severity of COVID-19 in Bangladesh." (PMID 38707035, 2024).
COVID-19 (continued). "Therefore, close monitoring of changes in IL-6 and ferritin concentrations in COVID-19 patients, especially those at high risk for VTE, is of great value in determining changes in the disease and in reducing the rates of severe illness, VTE morbidity and mortality." (PMID 38493138, 2024). "Furthermore, both hypertension and COVID-19 are associated with endothelial dysfunction, which may increase adhesion molecules and proinflammatory cytokines, including IL-6 and IL-17." (PMID 38424126, 2024). "In another study involving 60 COVID-19 patients, elevated levels of zonulin—a protein involved in regulating the tight junctions of the gastrointestinal tract—were linked to higher mortality, more severe illness, and increased levels of systemic inflammation markers, such as IL-6." (PMID 39518964, 2024). "Intriguingly, the number of known pre-existing conditions was also highly correlated with IL-6 (r=0.25, p<0.01), sIL-6R (r=0.21, p<0.05) and sgp130 (r=0.29, p<0.01) serum levels, underlining that pre-existing diseases are an important predictor of COVID-19 disease course." (PMID 39835136, 2024). "Similarly, IL-6 is involved in the regulation of immune response to viral infections and is associated with the onset of cytokine storm syndrome associated with severe COVID-19 cases." (PMID 38251210, 2024). "Additionally, systemic inflammation caused by COVID-19, such as complement C3 decrease and IL-6, TNF-α increase, are risk factors for long-term lung symptoms and leads to diffuse parenchymal changes in the lungs, including alveolar damage, exudation, and pulmonary fibrosis." (PMID 39149538, 2024). "Furthermore, early on during the COVID-19 pandemic, IL-6 inhibition was used as an investigational treatment, which disrupts the intestinal barrier, and has been associated with a higher incidence of coinfections in COVID-19 patients." (PMID 39037272, 2024). "Furthermore, it is conceivable that the dysregulation of immunological mediators implicated in COVID-19, including IL-6, sIL-6R, and sgp130, may contribute to varied prognoses and responses to pharmacological interventions such as tocilizumab and steroids." (PMID 39063569, 2024). "However, it was suggested that TSH, rather than fT3, had prognostic significance, as low TSH levels were associated with high levels of the inflammatory cytokine interleukin-6 (IL-6), suggesting that COVID-19 may be linked to a high risk of thyrotoxicosis." (PMID 39767735, 2024). "Previous studies have shown that the severity of COVID-19 is linked to the levels of interleukin(IL)-2, IL-6, IL-8, and tumour necrosis factor-α (TNF-α), and alterations in the expression of these inflammatory cytokines may occur in the early stages of SARS-CoV-2 infection." (PMID 38726341, 2024). "The cut-off IL-6 value of 19.5 pg/mL exhibited equal sensitivity and specificity with the highest positive predictive value of 63.2 pg/mL; therefore, this value was used to create the IL-6-based COVID-19 severity [IBC-S] score to determine the risk of the need for HFNC." (PMID 38394183, 2024). "Systemic and brain inflammation in patients with COVID-19 is associated with elevated levels of the same pro-inflammatory molecules that were increased following experimental dsRNA exposure in the current study, including IL-6, TNF-α, and complement C314,15,75." (PMID 37704739, 2023). "We therefore performed candidate screening for biomarkers in serum that predict a change in IL-6 as a surrogate for COVID-19-associated inflammatory dysregulation by applying a machine-learning approach to serial blood measurements in five severe COVID-19 disease courses." (PMID 37834869, 2023). "Therefore, it could be suggested that COVID-19 patients with downregulated miR-146a expression are expected to have elevated levels of pro-inflammatory cytokines, specifically IL-6, and increased susceptibility to cytokine storms." (PMID 36768701, 2023).
COVID-19 (continued). "In fact, although the data about MDRB colonization in COVID-19 are scant, the empirical treatment with broad spectrum antibiotic therapy and biologics that target and inhibit cytokines, such as IL-1 and IL-6, could raise the risk of MDRB colonization in these patients." (PMID 36978365, 2023). "Our data are consistent with those obtained from a cohort of patients with COVID-19 who were aged and/or had high-risk comorbidities, in whom low levels of Plg were associated with worse prognostic parameters such as higher levels of IL-6, CRP, and markers of organ dysfunction." (PMID 36917195, 2023). "Similarly to other cytokines (IL-6, TNFα), changes in the concentrations of chemotactic cytokines and GFs can be potentially useful diagnostic or prognostic markers and promising therapeutic targets for monitoring COVID-19 progression." (PMID 38239363, 2023). "Firstly, IL-6, obesity (each p < 0.05), and severe course of disease (p < 0.001) were significantly and independently associated with the percentage of pulmonary infiltrates in COVID-19, opposite to age, chronic pulmonary disease, and chronic kidney disease (each p = n.s)." (PMID 37733154, 2023). "Although the pathogenesis of COVID-19 severity remains unclear, numerous studies have shown an increase in the level of IL-6 and other proinflammatory cytokines in COVID-19 hospitalized patients and its association with the severity of the disease and mortality." (PMID 35076790, 2023). "The increase in the level of the NFκB subunit, i.e., p52 protein, observed in this study in patients with the fatal form of COVID-19 may suggest that it is caused by oxidative stress and the expression of cytokines, including IL-6, which stimulates inflammatory processes." (PMID 37686388, 2023). "Patients with ischemic heart disease, asthma, and high initial IL-6 and D-dimer levels were associated with a significant increased likelihood of mortality but clinical improvement was associated with a significant reduction in the likelihood of COVID-19 mortality." (PMID 37111389, 2023). "Notably, IL-6 has been closely associated with outcomes in COVID-19 patients." (PMID 38259435, 2023). "IL-6 promoter SNPs rs1800795 is polymorphic almost exclusively in Caucasians, and it has been suggested that genotype rs1800795GG, associated with high IL-6 production, might be protective against severe COVID-19." (PMID 36851291, 2023). "Furthermore, activation of TRPV-1 increases the release of several pro-inflammatory molecules, for example neuropeptide substance P (sP) and cytokines such as interleukin 6 (IL-6), exactly the molecules that have been implicated in the pathophysiological events associated with COVID-19." (PMID 36613152, 2023). "Elevated IL-6 levels are associated with severe disease and mortality in COVID-19 patients; however, pwCF show a constitutive reduction of IL-6 in the respiratory tract, which could serve as a protective factor from severe SARS-CoV-2 infection-related cytokine storms." (PMID 37250046, 2023). "Age, IL6 levels, and hospital stay may be factors influencing myocardial injury caused by COVID-19." (PMID 37564653, 2023). "Interestingly, in COVID-19 patients, pain, including headache, widespread myalgia, and back and neck pain, was linked to inflammation and cytokine storm, especially with the rapid release of the pro-inflammatory cytokines IL-6, IL-1RA, IL-10, IL21 and IL-22." (PMID 37175768, 2023). "In severe COVID-19, the immune system overactivation results in a “cytokine storm” characterised by the release of high levels of some cytokines into the circulation, especially Interleukin-6 (IL-6) and Tumour Necrosis Factor- α (TNF-α), causing a local and systemic inflammatory response." (PMID 36143014, 2022). "Additionally, COVID-19 is associated with elevated levels of IL-6." (PMID 35812392, 2022).